INS (insulin)
Diseases named in the same sentence as INS in open-access papers (continued):
Sharing a sentence is not in itself a finding about the gene and the disease.
cancer (continued). "However, we can speculate that insulin may modulate cancer development through both the insulin receptor and insulin like growth factor-1 receptor (IGF-1R)." (PMID 20436918, 2010). "Furthermore, we summarise the importance of the regulatory IGF/INS network in cancer, and discuss the possibilities and limitations of therapies targeting the IGF/INS axis with reference to ongoing clinical trials concerning the blockage of IGF1R in several types of cancer." (PMID 20924377, 2010). "Consequently, these signals might be potential targets for further biological investigation on how different doses and treatment conditions with TNF, EGF or insulin lead to different death/survival decisions in cancer cells." (PMID 17559646, 2007). "Consequently, the original aim was to investigate how the apoptosis signaling network was activated in response to different levels of TNF, EGF and insulin and how such differential activation contributes to antagonistic cellular decisions, such as cell death versus survival in cancer cells." (PMID 17559646, 2007). "We hypothesized that if a cancer patient were to be administered thyroid and insulin (to stimulate the sodium/potassium pump), glucose and potassium (TGIK), all in quantities to mimic those reached during an infectious challenge, inert lymphocytes would activate and destroy a tumor." (PMID 16111485, 2005). "Insulin substantially promotes the growth of malignant cells that overexpress the insulin receptor (INSR), and insulin excess has been recognised as a cancer-promoting factor in patients." (PMID 42286874, 2026). "Among the pathways most affected by statin-induced changes in kinase phosphorylation are insulin signaling, EGF–EGFR signaling, PI3K/AKT signaling, and the PD-L1/PD-1 immune checkpoint pathway in cancer." (PMID 40832614, 2025). "2-HB is a metabolic biomarker for various diseases, including insulin sensitivity, T2DM, major cardiovascular diseases, and cancer, and is involved in lipid oxidation and oxidative stress." (PMID 39852401, 2025). "Insulin and IGF‐1 receptors, which are abundantly present on cancer cells, facilitate the activation of key signaling pathways such as mitogen‐activated protein kinase and mammalian target of rapamycin." (PMID 39949980, 2025). "Insulin and insulin‐like growth factor‐1 (IGF‐1), which are elevated in obese individuals, act as potent mitogens and survival factors for cancer cells, stimulating proliferation, inhibiting apoptosis, and enhancing tumor cell migration and invasion." (PMID 39969135, 2025). "These pathways included the expression of PD-L1 in cancer and the PD-1 checkpoint pathway, AGE-RAGE signaling in diabetic complications, insulin secretion, insulin resistance, and the differentiation of T cells, B cells, and other cell types." (PMID 40595026, 2025). "The PI3K/AKT pathway, a key mediator of insulin and IGF‐1 signaling, promotes glycolysis and lipid biosynthesis, which are crucial for rapidly dividing cancer cells." (PMID 40387523, 2025). "Alongside this, a dose-specific preoperative administration of metformin to patients diagnosed with EC significantly decreased the level of insulin, IGF-1, glucose, and leptin, thereby inhibiting the cancer cell progression." (PMID 39996906, 2025). "Insulin-expressing cells, particularly the INS+ cell cluster, also showed higher expression of specific oncogenes and cancer-related genes, including genes that have been prioritized for targeted therapy in humans." (PMID 40438247, 2025). "Given the magnitude of insulin and IGF-1 actions, the whole cascade needs to be tightly regulated to prevent metabolic disruptions and cancer development." (PMID 40141412, 2025). "Metformin also influences the PI3K/AKT pathway, commonly dysregulated in cancer, by lowering insulin and insulin-like growth factor (IGF) levels, reducing cancer cell survival signals." (PMID 40283503, 2025).
cancer (continued). "In total, 17 studies including 197 patients with cancer and CAC reported measures on fasting glucose and insulin and were included in the analysis." (PMID 41367198, 2025). "Metformin exerts anti‐cancer effects by suppressing IGF‐1 and insulin signaling pathways, which are key regulators of cell growth, metabolism, and tumor progression." (PMID 40387523, 2025). "There were also significant interactions between insulin-expressing cancer cells and immune cells, namely CD40LG (INS+FOSlow, INS+) − CD40 (B cell) and APP (INS+) − TREM2 + TYROBP (macrophage)." (PMID 40438247, 2025). "This systemic insulin excess, along with the potential mitogenic effects of insulin and some insulin analogues, may promote tumour growth, possibly via stimulation of the insulin-like growth factor 1 (IGF-1) axis, a pathway implicated in the pathogenesis of several cancers." (PMID 41334715, 2025). "By reducing circulating glucose and insulin levels, KD suppresses the insulin/IGF-1 signaling axis, a key driver of cancer cell proliferation and survival." (PMID 40428567, 2025). "By activating AMPK and reducing insulin and IGF-1 signaling, metformin mirrors some of the cancer-protective effects of CR, promoting cellular resilience and reducing cancer-promoting pathways." (PMID 39940361, 2025). "Insulin and insulin-like growth factor-1 (IGF-1) signaling pathways also play a crucial role in cancer development as their overactivation can promote cell proliferation and survival." (PMID 40428567, 2025). "Given the crucial role of insulin metabolism in T2DM and the TGF-beta signaling pathway in various cancers, these findings suggest that these DEGs are important for the progression of both diseases." (PMID 41372957, 2025). "By reducing insulin levels, SGLT2 inhibitors help to restore metabolic balance and reduce this pathway’s contribution to cancer progression." (PMID 40227756, 2025). "In conclusion, insulin and IGF-1 signaling pathways are critical drivers of cancer development and progression, and their dysregulation is strongly influenced by diet and nutrition." (PMID 40428567, 2025). "Metformin also modulates the insulin/IGF-1 signaling pathway, which is frequently overactive in cancer cells, lowering insulin and IGF-1 levels and thereby reducing PI3K/AKT/mTOR pathway activation, which decreases cell growth and induces apoptosis." (PMID 39272875, 2024). "Several studies have provided evidence to support that the insulin/IGF-2/IR-A pathway and its downstream signaling cascades serve as specific and distinct target sites in malignant tumors." (PMID 38331804, 2024). "Additionally, IR may mediate cancer progression via the insulin/insulin-like growth factor axis." (PMID 39180548, 2024). "Lowering circulating growth factors (i.e., insulin and IGF) is a therapeutic approach to improving anti-cancer drug efficacy, and dietary protein abundance can drive the production of these growth factors." (PMID 39702320, 2024). "Thus, an excess of insulin could potentially be beneficial to cancer cell growth." (PMID 38374190, 2024). "The stimulation of the KATP activity by growth factors, insulin, and the KATP channel opener minoxidil induces cell proliferation and cancer progression in animals and humans." (PMID 39200356, 2024). "Receptors for insulin and IGF-1 are expressed in most cancer cells, and receptor activation results in signaling pathways capable of stimulating cancer cell proliferation, protection from apoptotic stimuli, invasion and metastasis." (PMID 37347429, 2024). "snATAC-seq revealed enhanced chromatin accessibility in cancer, lipid, TCA-cycle, and insulin-resistance pathways in fasted Per1cLKO hepatocytes." (PMID 39412985, 2024).
cancer (continued). "The significantly elevated insulin levels overly stimulate IGF-1 and both the Insr and the IGF-1R, resulting in increased survival of pre-malignant cells, heightened cancer cell proliferation, and resistance to apoptosis." (PMID 39596226, 2024). "Specifically, the IGF family consisting of insulin, IGF-1, and IGF-2 regulates cellular functions relevant to cancer, including mediating the growth and survival of cancer cells (i.e., Akt and mechanistic target of rapamycin (mTOR) signaling)." (PMID 40443827, 2024). "Ongoing trials are exploring amino acid-restricted diets, metformin targeting insulin secretion, or statins modulating lipid metabolism (NCT03889795, NCT03889795) as adjunct therapies for cancer patients." (PMID 39668159, 2024). "Insulin/IGF signaling plays a critical role in the development and progression of many human cancers." (PMID 39763653, 2024). "This increase in insulin promotes the activity of IGF-1, which also promotes cancer cell proliferation by inhibiting apoptosis." (PMID 40046187, 2024). "Elevated levels of insulin and IGF-1 contribute to the accelerated growth of colon cells, potentially leading to cancer development." (PMID 39201651, 2024). "KD reduces blood glucose and lowers insulin and IGF-1 activity and provides a metabolic strategy to potentially slow cancer cell expansion." (PMID 39534224, 2024). "Beyond metformin, other conventional anti-diabetic treatments, such as insulin, sulfonylureas (SUs), pioglitazone, and dipeptidyl peptidase-4 (DPP-4) inhibitors, have also been examined for their roles in cancer biology, though findings are often inconclusive." (PMID 39595655, 2024). "Elevated levels of insulin and insulin-like growth factor-1 (IGF-1) can promote cellular proliferation and inhibit apoptosis, further contributing to cancer development and progression." (PMID 39379738, 2024). "The Figure summarizes the way insulin and IGF-1 affect cell metabolism and possible cancer development." (PMID 38339407, 2024). "Our data suggest that EAPB02303 reduces the insulin signaling via PI3K-Akt, a cascade that is frequently aberrantly activated in many human cancers rendering it an attractive druggable target." (PMID 39063027, 2024). "High levels of glucose and insulin can increase the activity of various growth factors, such as insulin-like growth factor-1 (IGF-1), which can stimulate the growth and survival of cancer cells." (PMID 39048990, 2024). "In normoglycemic individuals, insulin secretion and IGF-1R activation are tightly regulated, resulting in a more controlled rate of cancer cell growth." (PMID 39290325, 2024). "Elevated insulin and IGF-1 levels are believed to play a role in the development of cancers by promoting cellular proliferation and inhibiting apoptosis—potentially allowing tumor growth, such as colon, renal, prostate, and endometrial cancer." (PMID 38339271, 2024). "Metformin influences insulin and insulin-like growth factors (IGFs), reducing plasma insulin and IGF-1 levels, known mitogen for cancer cells." (PMID 38474224, 2024). "This happens mainly via insulin/PI3K/Akt signaling and has been observed in the form of increased Akt in biopsies of cancer patients after Rapamycin treatment." (PMID 39456169, 2024). "Specific targeting of insulin and IGF receptors in cancer cells is a promising anti-cancer strategy." (PMID 39763653, 2024). "Concerning the mechanisms whereby the fasting-induced reduction in insulin, IGF1 and leptin mediates cancer cell sensitization to CBIs, we first focused on the expression of enzymes from the cholesterol biosynthesis pathway." (PMID 37907500, 2023). "Differences in hormonal levels of estrogen and insulin, growth factors such as IGF-1, and inflammatory mediators have been proposed as possible explanations for these differences in esophageal and other cancer incidence and survival." (PMID 36900690, 2023).
cancer (continued). "IR-A is a dual high-affinity receptor for insulin and IGF2 and represents the principal receptor for IGF2 in those cancers with IR-A overexpression." (PMID 36672737, 2023). "Some dietary factors, including carbohydrates, lead to the proliferation of cancer cells, including CRC, through alternations in insulin levels and circulating glucose, impaired glucose metabolism, insulin resistance, and hyperinsulinemia." (PMID 37069525, 2023). "First, adiposity tissue, especially visceral adipose can increase concentrations of serum insulin and insulin-like growth factor- I (IGF-I), and lead to leptin and adiponectin secretion, which play important roles in the pathogenesis of cancer." (PMID 36991401, 2023). "The top 5 enriched pathways include Longevity regulating pathway-multiple species, Insulin signalling pathway, Fatty acid elongation, Inflammatory mediator regulation of TRP channels and Proteoglycans in cancer." (PMID 37925496, 2023). "Among the known GLUTs, insulin-independent GLUT1 is widely distributed in different tissues, and often elevated in many cancer types." (PMID 38078007, 2023). "The direct impacts due to the overexpression of insulin resistance in specific tumor cell lines enhance the proliferative response to insulin, and ERK has been pointed out to be responsible for activating the cell cycle process in cancer cells." (PMID 37664840, 2023). "Given the differences between IRS1/2 and IRS4 at the molecular level, knowledge of the signaling pathways controlled by IRS4 may enable the design of new drugs for the treatment of cancer without causing deleterious effects on the regulation of insulin and/or IGF1 signaling cascades." (PMID 37760618, 2023). "A number of other RTKs, such as insulin/IGF receptors and EGFR, activate Akt in other cellular contexts such as growth and proliferation of various stem cells and mammalian cancer cells." (PMID 36647607, 2023). "Some of the proposed anti-tumor benefits of KD include inhibition of the insulin/insulin growth factor (IGF) pathway, alteration in cancer stem cell properties, and upregulation of metabolic signaling pathways, such as AMP kinase activation." (PMID 37375634, 2023). "Moreover, although we had excluded patients who had malignant tumor or severe immunosuppression (such as oral glucocorticoids treatment), concurrent medication (such as proton pump inhibitors or insulin sensitizing agents) or follow-up intervention may have influenced bone mineral density." (PMID 36747237, 2023). "Insulin and IGF, two genuine substrates of IDE, control critical pathways in energy metabolism and growth, especially for cancer cells." (PMID 35406791, 2022). "Moreover, in malignant tumours, significant insulin resistance may occur in the body, leading to abnormal transduction of plasma insulin signals related to the occurrence of malignant tumours and abnormal energy metabolism of central sensors and cells, thus inducing malignant tumours." (PMID 35431651, 2022). "Additionally, our data link the RNA binding proteins CUG-BP1 and MBNL1 with IR alternative splicing and this interplay between the two could further be exploited in therapeutic and mechanistic directions for other cancers and diseases for which insulin signaling is affected." (PMID 35017650, 2022). "Previous studies have shown that MAZ activates the expression of a variety of genes, including c-Myc, insulin, VEGF, and the RAS gene family in cancer cells." (PMID 35456450, 2022). "Furthermore, without a prospective evaluation, we could not quantify the effects on the BRCA-related cancer risk of the greater reduction of serum insulin observed in LOF variant carriers." (PMID 35356420, 2022).
cancer (continued). "Insulin is itself a mitogen and increases the bioactivity of insulin-like growth factors (IGF-1), which can promote cancer by inhibiting apoptosis and stimulating cell proliferation." (PMID 36429506, 2022). "Possible biological mechanisms through which physical activity could affect cancer progression include decreased levels of circulating sex hormones (e.g., estrogens, androgens), reduced systemic inflammation, and positive changes in metabolic markers (e.g., decreased insulin and glucose levels)." (PMID 36099282, 2022). "INS and PI3KR3 were among the top 100 genes judged by the feature importance weights of the pan-cancer XGBoost prediction model and were used as seed genes for the network propagation." (PMID 35106465, 2022). "Other hydrogels composed from polypeptides and polysaccharides are able to deliver cancer drugs to desired locations to prevent the spread of cancer, regenerate tissue that may have been damaged due to illness or injury, and delivery molecules such as insulin for diabetic patients." (PMID 35163339, 2022). "A dual increase of glucose and insulin is typical in PDA patients and is essential for cancer development and progression." (PMID 35252207, 2022). "CDR formation was examined in six cancer cell lines in response to epidermal growth factor (EGF) and insulin." (PMID 35799301, 2022). "In addition, when assessing the risk of breast and kidney cancer during treatment with canagliflozin, no significant increase in the risk of these cancers was found compared to a group treated with other antidiabetic drugs (insulin, metformin, sulfonylurea, pioglitazone)." (PMID 36497303, 2022). "INSR and IGF1R belong to Insulin/IGF System, which was known to affect the malignant behavior of cancer cells and was regulated by Glycans." (PMID 35752862, 2022). "The Netherlands Cancer Registry (NCR) PHARMO database was analyzed, and metformin users were compared with users of other non-insulin antidiabetic drugs (NIADs)." (PMID 36430639, 2022). "Numerous IDE substrates are highly relevant in the context of cancer, in particular IGF-II, insulin and CCL3." (PMID 35406791, 2022). "Metformin was found to reduce insulin levels, inhibit the insulin/IGF signaling pathway and alter cellular metabolism in normal and cancer cells." (PMID 36142321, 2022). "This phenomenon is particularly important in cancer cells, wherein TXNIP is often epigenetically silenced, thereby leading to a potentially amplified effect of both IGF1 and insulin on mitosis." (PMID 36291127, 2022). "Thus, obesity and overweight by increasing the proinflammatory cytokine release, promoting insulin resistance, altering the systemic metabolism, and inducing fibrosis, promote cancer initiation and development, making it a target of choice for the implementation of exercise in the cancer context." (PMID 36358820, 2022). "The action behind anti‐cancer effects of metformin is mainly a result of AMPK activation, mTOR inhibition, regulation of insulin and other AMPK‐independent pathways." (PMID 36052760, 2022). "In contrast, our study demonstrated that the MAPK4-AKT signaling cascade can be activated by both insulin and EGF, two key factors regulating physiology and diseases, including cancers." (PMID 35017531, 2022). "In our previous study, we observed that LLC cancer cell implantation into ND-fed lean C57BL/6 mice appeared to have a negligible effect on circulating levels of glucose, insulin and leptin." (PMID 36012397, 2022). "A previous study showed that following insulin stimulation in the insulin signaling pathway, SORBS1 mediated the functional transition of the insulin receptor from metabolism to cancer-related cell proliferation as well as migration." (PMID 35196185, 2022). "For all cancer sites, cases were more likely to have BMI≥30 kg/m2, and higher median values for leptin, CRP, and fasting insulin relative to controls." (PMID 35048536, 2022).